GREB1 (growth regulating estrogen receptor binding 1)
Diseases named in the same sentence as GREB1 in open-access papers (continued):
Sharing a sentence is not in itself a finding about the gene and the disease.
endometriosis (continued). "Although rs11674184 of GREB1 constitutes one of the most consistently associated SNPs with endometriosis in European ancestry populations, an absence of association with endometriosis in a cohort of 166 women has recently been reported." (PMID 32549322, 2020). "GREB1 also plays a role in endometriosis, which is 17-β estradiol-responsive." (PMID 32549322, 2020). "The association of GREB1 and KDR mQTLs with endometriosis risk in both endometrium and blood may suggest the biological mechanisms that increase endometriosis risk may not be specific to endometrium." (PMID 30871624, 2019). "Additionally, endometrial cancer appears to overlap genetically with endometriosis, and GREB1 mRNA levels are significantly higher in ectopic endometrium (endometriosis lesions) than in eutopic endometrium." (PMID 30154312, 2018). "The study, which is a systematic review of GWAS studies published by PubMed until December 31, 2019, indicates that variants of the genes WNT4 rs7521902, GREB1 rs13394619, FN1 rs1250248, IL1A rs6542095 and VEZT rs10859871 may affect the development of endometriosis." (PMID 34638893, 2021). "Similarly, meta-analyses conducted on four genome-wide association studies showed that rs13394619 in GREB1 was associated with endometriosis with little evidence of population-based heterogeneity." (PMID 32549322, 2020). "As observed when LXA4 was administered on D−1, IL-1β, COX-2, VEGF, MRP4, TGF-β1, TGF-β2, CYP19a1, ERα, GREB1 and c-Myc expression were significantly attenuated whereas MMP-9 and TGF-β3 were upregulated in endometriotic lesions in established endometriosis." (PMID 24587003, 2014). "However, the precise roles of GREB1 in normal endometrial physiology during pregnancy and pathology during endometriosis have not been determined." (PMID 38431630, 2024). "Similarly, genes shared between endometriosis, uterine fibroids, ovarian cancer, migraine and depression (RHOA, FOXP1, ESR1, WNT4, GREB1, FSHB), and endometriosis, migraine and asthma (IGF1, SMAD3, MFHAS1), were enriched in hormone receptor signalling and inflammation pathways, respectively." (PMID 37159502, 2023).
ovarian carcinoma (11 papers, 2018 to 2025). A malignant neoplasm originating from the surface ovarian epithelium. "This divergence is characterized by the activation of various cancer-associated pathways including an increase in Greb1 which was validated in fallopian tube epithelium and human ovarian cancers." (PMID 30418965, 2018). "GREB1 also plays a significant role in ovarian cancer, which is a gynecologic malignancy that causes an estimated 12,700 deaths in the United States (US) alone." (PMID 30154312, 2018). "GREB1 knockout mice are sub-fertile, while overexpression in ovarian cancer cell lines promotes a mesenchymal morphology." (PMID 40858568, 2025). "Microarray analysis revealed Greb1 as a substantially E2-upregulated gene in tumors derived from an E2-responsive mouse model of ovarian cancer." (PMID 39570927, 2024). "GREB1 (an estrogen receptor-regulated tumor promoter) overexpression in ovarian cancer cell lines increased cell proliferation and migration and promoted a mesenchymal morphology." (PMID 35631574, 2022). "In this sense, the inhibition of GREB1 expression in mouse ovarian cancer ascites (MAS) cell lines lowered their proliferation rate in vitro and raised survival time in mice engrafted with the MAS." (PMID 32549322, 2020). "Overall, the reported results indicate a major function for GREB1 in estrogen-dependent conditions in epithelial ovarian cancers." (PMID 32549322, 2020). "In ovarian cancer, GREB1 was upregulated in mouse tumors treated with 17-β estradiol and was overexpressed in human ovarian cancers corresponding to human ovarian surface epithelium, implying a function for GREB1 in human ovarian tumor advancement." (PMID 32549322, 2020). "We showed previously that stable GREB1 knockdown in mouse ovarian cancer cells reduces proliferation and prolongs survival of engrafted mice." (PMID 29973689, 2018). "Tumor xenograft studies using mouse ovarian cancer ascites (MAS) cells with elevated GREB1 expression indicated an increase in tumor growth and reduced median survival time." (PMID 30154312, 2018). "We have confirmed that the protein GREB1 appears in the pre-cancerous cells and is present in the majority of human ovarian cancers." (PMID 30418965, 2018). "To investigate the possible role of GREB1 in human ovarian cancers, we explored its expression using a public database (TCGA; via cBioPortal)." (PMID 29973689, 2018). "Greb1 stands out because it is a known E2-responsive gene in breast and ovarian cancer that drives tumour progression, and it is currently being investigated as an alternative prognosis marker for tamoxifen treatment." (PMID 30418965, 2018). "GREB1 protein expression was reported previously only in breast and uterine tissues; however, GREB1 mRNA was highly expressed in ovarian cancers." (PMID 29973689, 2018). "GREB1 overexpression in ovarian cancer cell lines increased cell proliferation and migration and promoted a mesenchymal morphology associated with increased Col1a2, which encodes a collagen I subunit." (PMID 29973689, 2018). "GREB1 is a known E2-responsive gene that we have previously shown to be over-expressed in human ovarian cancer relative to healthy human OSE and is known to promote cancer progression." (PMID 30418965, 2018). "In a tissue microarray analysis of ovarian cancer cases, GREB1 was expressed in 75–85% of epithelial ovarian cancer cells." (PMID 30154312, 2018). "Herein we have further explored the effects of GREB1 knockdown and overexpression in ovarian cancer cells." (PMID 29973689, 2018). "In a TMA of ovarian cancer cases, GREB1 was expressed in 75–85% of serous, endometrioid, mucinous, and clear cell carcinomas." (PMID 29973689, 2018). "Moreover, GREB1 promotes tumorigenicity in other hormone-dependent cancers, including ovarian cancer, prostate cancer, and endometrial cancer, as well as non–hormone-dependent cancers such as hepatoblastoma, the predominant pediatric hepatic neoplasm." (PMID 37611092, 2023).
ovarian carcinoma (continued). "GREB1 is present in the majority of ovarian cancers of all primary histological subtypes." (PMID 32549322, 2020). "GREB1 has also been reported to regulate proliferation in breast, prostate, and ovarian cancers." (PMID 30871624, 2019). "GREB1 knockdown prevents hormone-driven proliferation of several breast and prostate cancer cell lines and prolongs survival of mice engrafted with ovarian cancer cells, but its mechanism of action remains unclear." (PMID 29973689, 2018). "In this study, we explored GREB1 function in ovarian cancer." (PMID 29973689, 2018). "Similarly, in ovarian cancer, the hypomethylation of GREB1 was positively correlated with progression-free survival in ovarian cancer patients." (PMID 30154312, 2018). "While additional experiments are needed to elucidate the mechanism of action of GREB1, the prolonged survival of mice when GREB1 is suppressed provides initial evidence, suggesting that targeting GREB1 could have therapeutic efficacy in ovarian cancer." (PMID 29973689, 2018). "Several lines of evidence point to a role for GREB1 in the progress of epithelial ovarian cancer." (PMID 30154312, 2018). "However, we discovered that GREB1 was strongly expressed in both the nucleus and the cytoplasm of E2-treated mouse ovarian cancer cells." (PMID 29973689, 2018). "The ESR1-driven subset of E2 actions may be partially or entirely mediated by GREB1, which drives proliferation and tumour growth in mouse models of ovarian cancer." (PMID 29973689, 2018). "Given that GREB1 induction is dependent on E2 signalling, we used the CAG-TAg murine model of ovarian cancer to determine the impact of Esr1 deletion on survival of mice with and without exogenous E2 treatment." (PMID 29973689, 2018). "We also further investigated the function of GREB1 by examining GREB1 constitutive expression or knockdown and cell morphology, EMT, and migration in vitro, and on tumorigenicity in allograft models of ovarian cancer in vivo." (PMID 29973689, 2018). "GREB1 and ESR1 are co-expressed in normal female reproductive tissues, whereas GREB1 is present, with or without ESR1, in the majority of ovarian cancers of all major histological subtypes." (PMID 29973689, 2018).
prostate carcinoma (9 papers, 2017 to 2024). A carcinoma that arises from epithelial cells of the prostate gland. "In prostate cancer patients, tissue expression of GREB1 was associated with organ-confined prostate cancer and has been related with a positive prognosis." (PMID 32549322, 2020). "Additionally, a microarray analysis of prostate cancer samples from 33 patients showed that high GREB1 expression was associated with organ-confined disease, which is lower stage and a more favorable prognosis in prostate cancer." (PMID 30154312, 2018). "Our findings are consistent with the role of GREB1 in mediating estrogen-induced proliferation and androgen-induced proliferation in breast and prostate cancer cells respectively." (PMID 38431630, 2024). "Collectively, these data implicate GREB1 as an AR signal amplifier that contributes to prostate cancer disease progression and antiandrogen resistance." (PMID 30644358, 2019). "When the levels of the GREB1 protein were experimentally decreased in prostate cancer cells with a high androgen receptor output, the cells became less resistant to the antiandrogen drug." (PMID 30644358, 2019). "GREB1 is expressed in proliferating prostatic tissue and prostate cancer, which is regulated by androgens, and suppression of GREB1 blocks androgen-induced growth, suggesting GREB1 may be firmly involved in prostate cancer progression." (PMID 32549322, 2020). "A better understanding of how GREB1 and androgen receptor cooperate may also be useful for developing new drugs to treat prostate cancer." (PMID 30644358, 2019). "One curious observation is the fact that prostate cancers can maintain transcriptional heterogeneity as a stable phenotype, despite the fact that GREB1 expression drives a feed forward loop which, in principle, should result in an increased fraction of high AR output cells over time." (PMID 30644358, 2019). "Additionally, GREB1 responds to androgen in prostate cancer cells, and can stimulate the proliferation of breast, ovarian, and prostate cancer cells." (PMID 30154312, 2018). "GREB1 is required for hormone-stimulated growth in breast and prostate cancer cells and is a cofactor for ESR1 transcriptional activity, but its function otherwise remains unknown." (PMID 29973689, 2018). "However, recently it has been reported that GREB1 levels are elevated in the tumors of castration-resistant prostate cancer patients who have progressed undergoing enzalutamide treatment, providing evidence through xenograft models that GREB1 is required for in vivo enzalutamide resistance." (PMID 32549322, 2020). "Among upregulated genes, the gene Greb1 (growth regulating estrogen receptor binding 1), which is regulated by Esr1 in TM4 cells and primary Sertoli cells and is involved in hormone-responsive breast and prostate cancers, was increased by 3.5-fold only by the APAP + GEN mixture." (PMID 37443838, 2023). "Here we show that prostate cancers can amplify AR output through increased expression of the dual AR/ER coactivator GREB1, in the absence of genomic AR alterations." (PMID 30644358, 2019). "Although not as well studied as in breast, ovary, and prostate cancers, GREB1 may also play a role in uterine and testicular cancer." (PMID 30154312, 2018).
breast tumors (7 papers, 2018 to 2024). "Both GATA3 and GREB1 have been linked to estrogen receptor-positive breast tumors and have been proposed as markers for patient response to hormone treatment." (PMID 32605588, 2020). "Besides, the gene expression analysis from the TCGA database showed that HOIL-1 was positively correlated with ERα target gene expression including GREB1 and TFF1 in breast tumors (P <0.01, R = 0.17; P = 0.008, R = 0.08 respectively)." (PMID 34094957, 2021).
lung carcinoma (5 papers, 2017 to 2022). "GREB1 and other genes have been proposed as putative salivary biomarkers for the non-invasive detection of lung cancer as well as a target molecule of the Wnt/β-catenin pathway required for hepatoblastoma progression." (PMID 32549322, 2020). "The most interconnected genes were ESR1, GATA3 (DRG; breast, stomach, prostate, colorectal, lung cancer), and GREB1, all upregulated in ER+ samples, while ERBB2 which was downregulated." (PMID 32605588, 2020). "The logistic regression model combining the five mRNA biomarkers (CCNI, EGFR, FGF19, FRS2, and GREB1) can distinguish patients with lung cancer from normal controls (area under the receiver operating characteristic curve [AUC-ROC] = 0.925; sensitivity = 93.75%; specificity = 82.81%)." (PMID 35651679, 2022). "The non-invasive and affordable diagnosis of lung cancer can beaided by salivary mRNA biomarkers (CCNI, EGFR, FGF19, FRS2, and GREB1)." (PMID 37693919, 2022).
ovarian tumour (5 papers, 2018 to 2021). "17-β estradiol promotes ovarian tumor growth in mouse models with GREB1 a key mediator of this process, so the mechanism involved probably implies the upregulation of collagen I expression." (PMID 32549322, 2020). "We stained 40 human ovarian tumour samples and found detectable GREB1 in 75–85% of each of the various histological subtypes." (PMID 30418965, 2018). "In this study, we have shown that E2 promotes ovarian tumour growth in mouse models and have identified GREB1 as a key mediator of this process." (PMID 29973689, 2018). "We found that GREB1 mRNA levels correlated with ESR1 in ovarian tumours, but GREB1 protein levels did not correlate with ESR1 in the TMA." (PMID 29973689, 2018).
granulosa cell tumor (3 papers, 2023 to 2025). A slow-growing, malignant tumor, characterize by the presence of granulosa-like cells and Call-Exner bodies, that is almost always found in the ovary. "In fact, the mean age at diagnosis in GREB1-rearranged UTROSCTs was 55.7 years, which is similar to that for adult granulosa cell tumors and low-grade endometrial stromal sarcomas." (PMID 40150134, 2025). "Cyp11a1 acts upstream of the hormone biosynthetic process, and Greb1 has been reported to be induced by E2 in granulosa cell tumors through an ERα-dependent mechanism." (PMID 38031019, 2023). "It suggested that the ERα-dependent subset of E2 actions may be partially or completely mediated by GREB1, which promotes cell growth and survival in granulosa cell tumors." (PMID 39570927, 2024).
hepatoblastoma (3 papers, 2019 to 2023). Hepatoblastoma (HB) is a malignant hepatic tumor and is the most common pediatric liver cancer. "GREB1 is believed to be involved in hormone-dependent cancer growth, but it has recently been shown that GREB1 expression is also associated with hepatoblastoma, a hormone-independent tumor." (PMID 37658191, 2023). "Growth regulation by estrogen in breast cancer 1 (GREB1) is involved in hormone-dependent and -independent tumor development (e.g., hepatoblastoma)." (PMID 37658191, 2023). "Although GREB1 has been shown to be involved in the formation of hormone-dependent tumors, GREB1 was also found to be expressed in hepatoblastomas and hepatocellular carcinoma, which is a hormone-independent malignant tumor, and to promote cell proliferation." (PMID 37658191, 2023).
Infertility (3 papers, 2024 to 2026). "We found evidence at non-hormonal, pleiotropic, infertility loci for recent directional selection (EBAG9) and balancing selection (GREB1, INHBB, PCDH15)." (PMID 38562841, 2024).
melanoma (3 papers, 2018 to 2023). A malignant, usually aggressive tumor composed of atypical, neoplastic melanocytes. "RNA-seq from patient-derived xenografts (PDXs) of Japanese melanoma cases showed that GREB1 mRNA transcription starts at exon 19 and matched the GREB1 Is4, which encodes C-terminal half (amino acids 1003–1949)." (PMID 37658191, 2023). "The current study provided another example of GREB1 expression associated with a hormone-independent tumor, namely malignant melanoma." (PMID 37658191, 2023). "GREB1 Is4 silencing reduced melanoma cell proliferation in association with altered expression of cell proliferation-related genes in vitro." (PMID 37658191, 2023). "Taken together, these results suggest that GREB1 Is4 regulates melanoma cell proliferation in association with expression changes of cell proliferation-related genes." (PMID 37658191, 2023). "Thus, as well as MITF, GREB1 is expressed in benign nevi and tumor lesions of melanoma and their expression is correlated in both inter- and intra-tumors, and it is likely that GREB1 expression in tumor lesions is associated with aggressiveness of melanoma." (PMID 37658191, 2023). "Here, we show that the expression of the GREB1 splicing variant, isoform 4 (Is4), is mediated by MITF in melanoma cells." (PMID 37658191, 2023). "In the resected primary melanoma tumors, high expression of GREB1 (scores = 2 and 3) and MITF (score = 3) were observed in 30/89 (33.7%) and 34/89 (38.2%) tumors, respectively." (PMID 37658191, 2023). "MITF and GREB1 Is4 were strongly co-expressed in approximately 20% of the melanoma specimens evaluated (17/89 cases) and their expression was associated with tumor thickness." (PMID 37658191, 2023). "Tyr-CreER+/+; BRAFV600E/V600E; PTENflox/flox; Is4+/− and WT mice were crossed, and 4-OHT was applied to the entire back of their newborns, and the effect of GREB1 Is4 expression on melanoma development was evaluated using littermates." (PMID 37658191, 2023). "Candidate cancer genes that induce melanoma with the BRAFV600E mutation were screened using Sleeping Beauty (SB) transposon-mediated insertional mutagenesis in mice, and GREB1 was predicted as one of these genes." (PMID 37658191, 2023). "The clinicopathological parameters of melanoma cases with high GREB1 or MITF expression were compared to those with low GREB1 or MITF expression." (PMID 37658191, 2023). "Leflunomide, a DHODH inhibitor, was identified as an inhibitor of neural crest cell development by chemical screening, and A771726 also decreased melanoma cell growth in combination with GREB1 Is4 targeting." (PMID 37658191, 2023). "Taken together, these results suggested that GREB1 Is4 is primarily required for de novo pyrimidine synthesis in melanoma cells and has other regulatory roles for cell proliferation." (PMID 37658191, 2023). "MITF and GREB1 were strongly co-expressed in approximately 8/20 (40 %) of nevi and 17/89 (20%) of melanoma cases." (PMID 37658191, 2023). "GREB1 ASO was delivered mostly to melanoma tumors following systemic administration and reduced tumor size in a xenograft mouse model." (PMID 37658191, 2023). "The human melanoma patient TCGA and GTEx dataset revealed that GREB1 mRNA expression in primary and metastatic melanoma is higher than in normal skin tissue." (PMID 37658191, 2023). "In the serial sections of melanoma tissues expressing high GREB1 and MITF, the staining intensity for GREB1 and MITF was quantified and classified into four categories with pseudo-color." (PMID 37658191, 2023). "ATAC-seq of four Japanese melanoma PDXs revealed extensive chromatin accessibility around the 5’-upstream region of exon 19, where the transcription of GREB1 Is4 starts (UniProtKB, Q4ZG55-4; Ensembl, GREB1-206)." (PMID 37658191, 2023). "Overall GREB1 mRNA transcription was examined in melanoma cell lines by quantitative PCR (qPCR) using the four specific primer sets." (PMID 37658191, 2023).